VEGFA (vascular endothelial growth factor A)
Diseases named in the same sentence as VEGFA in open-access papers (continued):
Sharing a sentence is not in itself a finding about the gene and the disease.
cervical carcinoma (282 papers, 1999 to 2026). A carcinoma arising from either the exocervical squamous epithelium or the endocervical glandular epithelium. "In correlation, a recent TAN profiling study also reported that the VEGFA + SPP1+ subset was associated with worse clinical outcomes in 225 samples from 145 patients of 17 solid tumors including cervical cancer." (PMID 39971940, 2025). "The current investigation elucidated that CEBPD serves as an upstream regulatory factor for key genes, including MYC, IL6, JUN, RRM2, and VEGFA, all of which have been linked to an unfavorable prognosis in cervical cancer patients." (PMID 38926832, 2024). "Online bioinformatic tools were used to conduct the pre-investigation of linc00958/miR-185-5p/RSF-1 and predict the associations between RSF-1 and AKT1/GSK3β/VEGFA in cervical cancer." (PMID 36056431, 2022). "However, CA9, DERL3, and VEGFA genes were all upregulated while the opposite was reported for RNF130 in cervical cancer and was linked to unsatisfactory prognosis in the present research." (PMID 35935576, 2022). "We discovered that I-DXd, our in-house ADC targeting cervical cancer, effectively eliminates tumor cells through specific antigen recognition while concurrently depleting pro-tumor VEGFA + TANs via Fcγ receptor-mediated phagocytosis." (PMID 39971940, 2025). "Lastly, pazopanib inhibited several VEGFa-induced activities in cervical cancer (CC) cells, including EMT, migration, invasion, and anoikis resistance in CC cells." (PMID 41154409, 2025). "Four genes associated with survival of cervical cancer patients were selected by survival by univariate analysis: EGFR, TNF-α, VEGFA and MDM2 (P<0.1)." (PMID 40238841, 2025). "For example, LINC00707 promotes cervical cancer progression by regulating the miR-382-5p/VEGFA pathway and interacts with Smad proteins to regulate TGFβ signaling and cancer cell invasion." (PMID 40018039, 2025). "Conversely, miR-382-5p is downregulated in cervical cancer, where its predicted target, VEGFA, is highly expressed, promoting tumor growth and metastasis." (PMID 40168262, 2025). "It was observed that angelol-a significantly suppressed the expression of MMP2 and VEGFA, as well as inhibited cell migration and invasive behavior in human cervical cancer cells." (PMID 38751791, 2024). "On the other hand, VEGFA can also be a therapeutic target in various infertility mediated gynecological cancer like ovarian and cervical cancer." (PMID 36608061, 2023). "We found that decreased FN1 expression inhibited the phosphorylation of AKT and the expression of VEGFA in cervical cancer cells." (PMID 36999964, 2023). "ITGA5 promotes angiogenesis in cervical cancer by AKT/VEGFA axis and Fibronectin playscritical role in this pathway." (PMID 36999964, 2023). "Hsa_circ_0023404 and VEGFA were upregulated in cervical cancer tissues and were positively correlated with cervical cancer development, while miR-5047 silencing had the opposite role." (PMID 37234708, 2023). "Vitexin, a bioactive flavonoid compound, inhibits the angiogenesis of cervical cancer through the VEGFA/VEGFR2 pathway, contributing to inhibition of tumor progression." (PMID 37854285, 2023). "Our findings suggested that the angiogenic function of ITGA5 in cervical cancer was through increasing VEGFA expression." (PMID 36999964, 2023). "Overexpressing miR-5047 inhibits cervical carcinoma cell metastasis by downregulating VEGFA expression." (PMID 37957698, 2023). "The prognostic significance of VEGF-A (Vascular Endothelial Growth Factor-A) in cervical cancer is still a matter of scientific interest." (PMID 37512001, 2023). "In the current study, the novel designed model with four genes (RNF130, CA9, DERL3, and VEGFA) yielded high specificity and sensitivity in identifying prognosis in the cervical cancer." (PMID 35935576, 2022). "linc00958/miR-185-5p/RSF-1 modulates cisplatin resistance and angiogenesis through AKT1/GSK3β/VEGFA pathway in cervical cancer." (PMID 36056431, 2022).
cervical carcinoma (continued). "Mechanistically, linc00958 regulated miR-185-5p and RSF-1 and modulated cisplatin resistance in cervical cancer cells via targeting AKT1/GSK3β/VEGFA pathway." (PMID 36438563, 2022). "For example, it enhances cervical cancer metastasis and chemoresistance through VEGFA and autophagy signaling by sponging miR-5047." (PMID 36352482, 2022). "It has been reported to regulate miR-5047 and VEGFA in cervical cancer metastasis and chemoresistance." (PMID 35456001, 2022). "CC mechanism studies revealed that LINC00707 can combine with miR-331-3p to regulate expression of target VEGFA, and thus contribute to cervical cancer HT-3 and C-33A cell migration and invasion." (PMID 35155429, 2022). "Four genes were linked to the prognosis of ferroptosis in cervical cancer, namely, RNF130, CA9, DERL3, and VEGFA, which were obtained by univariate Cox regression analysis in the training set." (PMID 35935576, 2022). "hsa-circ 0023404 sponging miR-5047 elevated progression and chemoresistance in cervical cancer via VEGFA and autophagy signaling." (PMID 35127342, 2022). "The functional study shown that expression of AK4, HK2, P4HA1, TGFBI and VEGFA can regulate the proliferation, migration, and invasion ability of cervical cancer cells." (PMID 34217310, 2021). "The results obtained with RT-PCR and immunohistochemistry assays both showed that AK4, HK2, P4HA1, TGFBI and VEGFA were all highly expressed in these cervical cancer tissue samples." (PMID 34217310, 2021). "In conclusion, we confirmed that LINC00707 functioned as an oncogene in cervical cancer through forming the LINC00707/miR-382-5p/VEGFA axis." (PMID 34258298, 2021). "The colony formation and transwell assays results showed that reduced AK4, HK2, P4HA1, TGFBI and VEGFA expression, which significantly inhibited proliferation, migration and invasion ability of cervical cancer cells." (PMID 34217310, 2021). "In conclusion, our findings evidenced the significant role of LINC00707-miR-382-5p-VEGFA network in cervical cancer and it can provide an attractive target." (PMID 34258298, 2021). "The functional study shown that expression of AK4, HK2, P4HA1, TGFBI and VEGFA can regulate the proliferation, migration, and invasion ability of cervical cancer cells in vitro." (PMID 34217310, 2021). "Another study also elucidated that inhibition of VEGFA as well as its receptor and the signal transduction pathway can inhibit tumor growth in cervical cancer." (PMID 32983957, 2020). "Mir-203, which was downregulated in the hemangiosarcoma samples, has been shown to be a tumor suppressor that targets VEGFA, with increased expression of mir-203 leading to suppression of VEGFA in cervical cancer." (PMID 27912752, 2016). "Further, the analysis revealed VEGFA and IL-6 proteins as the distinctly high degree nodes in the disease network, which are known to manifest a major contribution in promoting cervical cancer." (PMID 26308848, 2015). "In this study, we have investigated the role of endoglin (CD105), a regulator of transforming growth factor (TGF)-β1 signalling on endothelial cells, basic fibroblast growth factor (bFGF) and vascular endothelial growth factor-A (VEGF-A) in cervical cancer." (PMID 19352388, 2009). "EGFR, TNF-α, and VEGFA are the key targets related to the prognosis of cervical cancer." (PMID 40238841, 2025). "In addition, new research results confirm that the LINC00707 lncRNA-mediated miR-382-5p/VEGFA pathway plays an important role in cervical cancer." (PMID 40264452, 2025). "Furthermore, a high GSVA score for VEGFA+ TANs correlated with a poorer clinical prognosis in cervical cancer patients according to the TCGA database." (PMID 39971940, 2025). "Notably, crinamine also exerts anti-angiogenic activity by inhibiting VEGFA protein secretion and vascular development in zebrafish embryonic cervical cancer cells." (PMID 38751791, 2024).
cervical carcinoma (continued). "Similarly, miR-5047 significantly inhibit cervical cancer metastasis and chemoresistance by down-regulating VEGFA." (PMID 39309008, 2024). "Integrin α5 (Itga5) was also reported to promote angiogenesis through VEGFA in cervical cancer." (PMID 39000126, 2024). "Furthermore, experimental models in vitro suggest that ITGA5 promotes angiogenesis in cervical cancer via the AKT/VEGFA pathway." (PMID 36999964, 2023). "Moreover, we observed that the level of VEGFA in cervical cancer cells were significantly decreased after downregulation of p‐AKT by AKT inhibitor (MK2206 2HCI), confirming that the AKT pathway modulates VEGFA." (PMID 36999964, 2023). "Our results showed that the AKT pathway modulated VEGFA in cervical cancer cells." (PMID 36999964, 2023). "Moreover, to further verify the influence of FN1 on AKT pathway and the expression of VEGFA in cervical cancer cells, we performed Western Blotting to evaluate the expression of AKT, p‐AKT, and VEGFA in the tumor cells transfected with siFN1 or siNC." (PMID 36999964, 2023). "VEGFA expression impacts cervical cancer cells’ apoptosis, proliferation, migration, and invasion." (PMID 36765810, 2023). "Further, linc00958/RSF-1 downregulation or miR-185-5p upregulation could alleviate the cisplatin resistance and tube formation in cervical cancer cells via AKT1/GSK3β/VEGFA pathway." (PMID 36056431, 2022). "Then, we explored the feasible relationship between miR-382-5p and VEGFA in cervical cancer." (PMID 34258298, 2021). "miR-203 can inhibit cervical cancer growth and angiogenesis through targeting VEGFA." (PMID 34258298, 2021). "Furthermore, to verify the accuracy of the 5-gene signature, we examined the expression of the signature genes (AK4, HK2, P4HA1, TGFBI and VEGFA) in clinical samples from 10 cervical cancer patients by qPCR and IHC analysis." (PMID 34217310, 2021). "Our findings indicated that LINC00707 and miR-382-5p could be used as novel markers of cervical cancer and were potential therapeutic targets for cervical cancer treatment via modulating VEGFA." (PMID 34258298, 2021). "Moreover, the results of qPCR and immunohistochemistry staining assay revealed that the expression of AK4, HK2, P4HA1, TGFBI and VEGFA is high in cervical cancer." (PMID 34217310, 2021). "We could conclude LINC00707 induced cervical cancer development via regulating miR-382-5p and VEGFA." (PMID 34258298, 2021). "Moreover, the result of RT-PCR and immunohistochemistry demonstrated that AK4, HK2, P4HA1, TGFBI and VEGFA were all highly expressed in these cervical cancer tissue samples." (PMID 34217310, 2021). "miR-144 can restrain cervical cancer growth and metastasis through targeting VEGFA." (PMID 34258298, 2021). "Furthermore, as we displayed, cervical cancer cell apoptosis, proliferation, migration, and invasion were all impacted by VEGFA." (PMID 34258298, 2021). "Then, we predicted that LINC00707 could serve as a molecular sponge for miR-382-5p to modulate VEGFA expression in cervical cancer." (PMID 34258298, 2021). "These displayed miR-382-5p inhibited cervical cancer cell growth via targeting VEGFA." (PMID 34258298, 2021). "Thus, we can reasonably hypothesize that TANs with these 12 significant TAN-related target genes are defined as VEGFA + TANs, which appear to be an immunosuppressive population in the advanced cervical cancer TME." (PMID 39971940, 2025). "The impact of these risk factors not only enhances clonogenesis and invasion of cervical cancer cells but also induces inflammation by affecting TNF-α and NF-kB signaling, resulting in the modulation of IL-6 and the activation of vascular endothelial growth factor (VEGFA)." (PMID 38956668, 2024). "Thus, the inhibition of VEGFA expression could lead to the inhibition of cell migration and invasive motility in cervical cancer cells while the PTGS2 (COX2) protein, located in the cytoplasm, is downregulated in cervical cancer tissue." (PMID 36765810, 2023).
cervical carcinoma (continued). "Thus, we hypothesized LINC00707 functioned as a novel biomarker in cervical cancer via modulating miR-382-5p and VEGFA." (PMID 34258298, 2021). "GO and KEGG enrichment analysis of key targets predicted the cancer pathway, PI3K-AKT-MDM2 expression pathway, VEGFA signaling pathway, and TNF signaling pathway for cervical cancer." (PMID 40238841, 2025). "In conclusion, our results suggested that JAM3 promotes cervical cancer cell migration and invasion by activating the HIF-1α/VEGFA pathway." (PMID 38760803, 2024). "To investigate the relationship between angiogenesis and cuproptosis in cervical cancer, we identified two types of cells, FDX1 + tumor/epithelial cells and VEGFA + tumor/epithelial cells, and conducted cell-cell communication analysis." (PMID 38200479, 2024). "The PPI network showed that IL6, VEGFA, and FGF2 are the key targets of seabuckthorn polysaccharides in the prevention and treatment of cervical cancer." (PMID 36845055, 2023). "In normal cervical tissue, the expression of VEGFA and its isoform (VEGF165) is low but is upregulated in cervical cancer tissue." (PMID 36765810, 2023). "Vascular endothelial growth factor A (VEGFA) is involved in the VEGF signaling pathway, and we have discussed its roles in COVID-19 and cervical cancer above." (PMID 36016559, 2022). "In cervical cancer, human papillomavirus (HPV) mediates the activation of VEGF-VEGFR pathway by promoting the expression of VEGFA, thus promoting tumor angiogenesis." (PMID 32655637, 2020). "The moderate or high expression rate for VEGFA was 35.7% (n = 15), with 19 patients (45.2%) exhibiting moderate or high immunohistochemical staining for VEGFB in the cytoplasm of cervical cancer cells." (PMID 28072723, 2017). "The outcomes of this assessment substantiated our preliminary observations, revealing the upregulation of RRM2 and VEGFA, alongside the downregulation of RFC4, EXO1, PCNA, TOP2A, and TYMS in cervical cancer tissues relative to normal cervical epithelial tissues." (PMID 38926832, 2024). "Here, we identify ITGA5 as the most survival‐related integrin superfamily member in cervical cancer and unravel its role in sprouting angiogenesis and VEGFA expression regulation, suggesting that ITGA5 is a potential mediator of angiogenesis in cervical cancer." (PMID 36999964, 2023). "Likewise, in cervical cancer HT-3 and C-33A cells, LINC00707 functions as an miRNA sponge to restrain levels of miR-382-5p and elevate expression of VEGFA to result in more intense cell proliferation." (PMID 35155429, 2022). "The findings obtained from qRT-PCR illustrated that the expression levels of VEGFA, CA9, and DERL3 in cervical cancer specimens were dramatically elevated in contrast with those in normal specimens, whereas the expression levels of RNF130 were lower contrasted to those in normal specimens." (PMID 35935576, 2022). "Subsequently, lack of VEGFA expression reversed the influence of miR-382-5p knockdown on cervical cancer cells." (PMID 34258298, 2021). "The expression levels of FNDC3A, VEGFA, OPN3 and CPE were all high in cervical cancer tissues." (PMID 34630524, 2021). "Our bioinformatics analyses show that miR-106b could promote cervical cancer progression by modulating the expression of GSK3B, VEGFA, and PTK2 genes." (PMID 30275981, 2018). "Our findings suggest that CA, by suppressing VEGFA, may possibly contribute to the reduction of SNAI1 transcription in cervical cancer cells, but further mechanistic study is needed." (PMID 29337896, 2018). "Furthermore, we found that three of the signature genes (FNDC3A, VEGFA or CPE) function as oncogenes to promote the proliferation, invasion and migration of cervical cancer cells and could be potential therapeutic targets for CC." (PMID 34630524, 2021).
Obesity (240 papers, 2009 to 2026). Accumulation of substantial excess body fat. "VEGFa is abundant in BAT, and decreased expression of VEGF caused by obesity may be related to functional hypoxia, leading to mitochondrial dysfunction and the accumulation of lipid droplet whitening of BAT." (PMID 34082784, 2021). "Obesity is associated with angiogenesis, in which VEGFA plays a key role." (PMID 34088886, 2021). "Additionally, VEGFA is directly associated with the regulation of obesity." (PMID 38920980, 2024). "Consistent with our mouse data, both VEGFA and KDR gene expression exhibited a clear upward trend in obesity, while VEGFA was significantly upregulated in prediabetes/T2D, showing a strong correlation with hemoglobin A1c (HbA1c) levels." (PMID 40488531, 2025). "Taken together, obesity induces vascular alterations in a depot-specific manner, with a differential response of VEGFA in early and later stages of tissue expansion." (PMID 40562785, 2025). "To gain understanding of VEGFA expression patterns in the context of obesity, we performed immunostaining for VEGFA in sWAT." (PMID 40562785, 2025). "Taken together, these observations point towards a complex dichotomous response of VEGFA and its effect on angiogenesis and vascular maintenance in the context of obesity depending upon the stage of WAT expansion." (PMID 40562785, 2025). "In experimental models of genetically induced obesity, different results have been reported regarding the effects of VEGFA on I/R injury." (PMID 39839674, 2024). "Under PH + IR conditions, VEGFA exacerbated hepatocellular damage in steatotic livers in an experimental model of genetically induced obesity." (PMID 39839674, 2024). "We have previously showed that BAT becomes hypoxic and exhibits a functional decline in obesity due to a reduction in vascular endothelial growth factor a (VEGF-A) levels in this organ." (PMID 39160276, 2024). "Commonly, expression level of the VEGFA increases during obesity, and neutralization of VEGFA relieves the metabolic disorders occurred by diet." (PMID 37069607, 2023). "Significant positive correlations existed between the expression levels of WNT10B, sXBP1, and VEGFA, considering all obesity groups (r = 0.7, p = 0.0001 and r = 0.3, p = 0.01, respectively)." (PMID 37219669, 2023). "Estrogen receptor alpha (ESR1) regulates angiogenesis of adipose tissue via VEGFA, and ESR1-deficient mice are exposed to insulin resistance and obesity." (PMID 35052852, 2022). "VEGFA circulating levels are raised in obesity and secretion from omental VAT seems to be the main contributor." (PMID 35216509, 2022). "We also found that obesity increased (p = 0.038) plasma levels of vascular endothelial growth factor A (VEGFA)." (PMID 34445187, 2021). "In mouse model, it has been demonstrated that over expression of VEGFA in adipose tissue provide protection against high fat diet induced obesity and insulin sensitivity." (PMID 34429108, 2021). "The targeted blockade of VEGFA165b improved angiogenesis in vWAT, which partially explains the paradoxical decrease in capillary density concurrent with increased VEGFA levels in obesity." (PMID 33327460, 2020). "When we specifically analyzed nHT patients with obesity we observed that VEGFA was significantly reduced in SAT." (PMID 33022994, 2020). "It should also be noted that the effect of AT-specific overexpression of VEGFA on diet-induced obesity is partly due to the browning of WAT and the elevated thermogenesis in these models." (PMID 33327460, 2020). "Cardiovascular complications of obesity are on the rise; therefore, this study set out to determine if adipose-specific ablation of vascular endothelial growth factor-A (VEGF-A) plays a role in the maintenance of aortic structure and function." (PMID 31258484, 2019).